GFPT2 (glutamine--fructose-6-phosphate transaminase 2)
Diseases named in the same sentence as GFPT2 in open-access papers (continued):
Sharing a sentence is not in itself a finding about the gene and the disease.
gastric cancer (3 papers, 2016 to 2025). A primary or metastatic malignant neoplasm involving the stomach. "In gastric cancer, recent studies show that high GFPT2 expression correlates with increased tumor invasion and poor patient outcomes, while downregulation of GFPT1 in the same cancer type is similarly associated with EMT, invasion, and adverse prognosis." (PMID 40830088, 2025). "Given the established links between GFPT isoforms and tumor progression, the contrasting roles of GFPT1 and GFPT2 in gastric cancer warrant further investigation." (PMID 40830088, 2025).
ovarian carcinoma (3 papers, 2022 to 2025). A malignant neoplasm originating from the surface ovarian epithelium. "Future studies should go further into these pathways to better understand GFPT2’s influence on ovarian cancer cell biology and chemosensitivity." (PMID 40291779, 2025). "This study investigated the role of glutamine-fructose-6-phosphate transaminase 2 (GFPT2) in the response of epithelial ovarian cancer cells to paclitaxel, a standard chemotherapy drug." (PMID 40291779, 2025). "Overall, our findings indicate that GFPT2 plays a pivotal role in modulating the NF-κB signaling pathway, which impacts paclitaxel resistance in ovarian cancer and highlights its broader implications in tumor progression and inflammatory responses." (PMID 40291779, 2025). "While offering new insights into the role of GFPT2 in modifying paclitaxel resistance in ovarian cancer cells, this work has certain limitations." (PMID 40291779, 2025). "In our exploration of GFPT2’s mechanistic influence on the reaction of ovarian cancer cells to paclitaxel, we discovered a pivotal connection between GFPT2 expression and the NF-κB signaling pathway, which was reported to be a central modulator in cells’ responses to chemotherapeutic agents." (PMID 40291779, 2025). "To gain insight into the broader clinical implications of GFPT2 expression concerning the response to paclitaxel and survival rates in ovarian cancer patients, we reviewed data from individuals within TCGA database who underwent chemotherapy treatments containing paclitaxel." (PMID 40291779, 2025). "These insights reveal the nuanced interplay between GFPT2 and the NF-κB pathway in regulating ovarian cancer cells’ sensitivity to paclitaxel, presenting the pathway’s modulation by GFPT2 as a promising avenue for therapeutic strategies in ovarian cancer treatment." (PMID 40291779, 2025). "Taken together, these results indicate that GFPT2 influences the NF-κB pathway, at least partially, by regulating NKX3-2, providing fresh perspectives on the intricate signaling networks within ovarian cancer cells." (PMID 40291779, 2025). "Among the identified proteins, significant enhanced expression of GFPT2, FLNA, TGFBI (CDGG1), ITGA2 predicted unfavorable prognosis in ovarian cancer patients." (PMID 36463238, 2022). "While there are no specific clinical trials targeting GFPT2 in the context of paclitaxel resistance in ovarian cancer, ongoing clinical trials explore the role of NF-κB inhibitors in various cancer treatments." (PMID 40291779, 2025). "Although specific GFPT2 inhibitors are not yet in clinical use, the understanding of their roles in cancer progression and resistance suggests that targeting GFPT2 could be a viable strategy in the future management of ovarian cancer." (PMID 40291779, 2025).
serous ovarian cancer (3 papers, 2022 to 2024). "GFPT2 has been reported to initiate EMT in serous ovarian cancer by activating the hexosamine synthetic pathway to enhance the nuclear localization of β-catenin." (PMID 36463238, 2022).
Hyperglycemia (2 papers, 2017 to 2018). An increased concentration of glucose in the blood. "While loss of Gck in hepatocytes and β cells is linked to hyperglycemia, altered Gfpt2 expression in Nrf2−/− mice may counterbalance this effect and maintain cardiac glucose homeostasis." (PMID 28673258, 2017).
metastatic tumor (2 papers, 2021 to 2025). "In metastatic tumors, GFPT2 expression is also favorably associated with EMT-promoting transcription factors, including SNAIL, TWIST, and VIMENTIN." (PMID 40830088, 2025). "Among the 11 patients that showed GFPT2 expression in the primary tumor, 64% (n = 7) demonstrated concordant expression of GFPT2 in at least one metastatic tumor." (PMID 33941787, 2021). "Gene expression profiling reveals that GFPT2 is a metabolic signature of mesenchymal cancer cell lines, upregulated in EMT and prominent in metastatic tumors exhibiting EMT." (PMID 40830088, 2025). "For the 26 patients lacking GFPT2 expression in the primary tumor, 77% (n = 20) also did not express GFPT2 in any of the examined metastatic tumors." (PMID 33941787, 2021). "We demonstrated that glutamine-fructose-6-phosphate transaminase 2 (GFPT2), the rate-limiting enzyme in HBP, is expressed on protein level in a subset of LMS and the expression of this enzyme is frequently retained in patient-matched primary and metastatic tumors." (PMID 33941787, 2021).
bladder tumor (1 paper, 2025). "In addition, GFPT2, another isoform of GFPT rate-limiting enzyme in the HBP, was not changed in mouse bladder tumor tissues and cell lines." (PMID 40740652, 2025).
chronic renal insufficiency (1 paper, 2010). "Association of SNPs in RAGE and GFPT2 suggest that the genes involved in modulation of oxidative pathway could be major contributor to diabetic chronic renal insufficiency." (PMID 20353610, 2010).
infantile-onset epilepsy (1 paper, 2021). Epilepsy starting in the first 12 months of life, including self-limiting and refractory seizures, and epilepsies with and without developmental disorders. "In the chronic stage of infantile-onset epilepsy, DIANA-mirPath identified two gene targets of miR-451-5p (Prps2—Phosphoribosyl Pyrophosphate Synthetase 2 and Gfpt2—Glutamine-Fructose-6-Phosphate Transaminase 2) involved in multiple metabolic pathways." (PMID 33958654, 2021).
invasive breast carcinoma (1 paper, 2022). A carcinoma that infiltrates the breast parenchyma. "GFPT2 has previously been identified as part of the mesenchymal metabolic signature genes and associated with invasive breast cancer mesenchymal phenotypes on the mRNA level." (PMID 34923141, 2022).
leiomyosarcoma (1 paper, 2025). An uncommon, aggressive malignant smooth muscle neoplasm, usually occurring in post-menopausal women. "Elevated GFPT2 levels are consistently observed from primary to metastatic leiomyosarcoma, underscoring its critical role in cancer metastasis." (PMID 40830088, 2025). "Additionally, active GFPT2 expression is associated with c-Myc target genes, suggesting that HBP-induced O-GlcNAcylation stabilizes c-Myc in leiomyosarcoma." (PMID 40830088, 2025).
lymph node metastasis (1 paper, 2022). "In addition, more cases of lymph node metastasis were positively correlated with higher GFPT2 levels." (PMID 35330716, 2022).
serous ovarian cystadenocarcinomas (1 paper, 2022). "Amongst the proteomics identified and validated genes, the expression of TGFBI significantly positively correlated with the expression of GFPT2, FLNA, G6PD, ITGAV, ITGA1 and ITGA2 within the serous ovarian cystadenocarcinomas in TIMER database." (PMID 36463238, 2022).
synucleinopathies (1 paper, 2024). "Taken together, these data show that hypo-N-glycosylation in synucleinopathy occurs through deficits in GFPT2, and restoring its expression can rescue lysosomal function, reduce α-syn, and improve neuronal health." (PMID 38897986, 2024). "For synucleinopathies, future work aimed at increasing the enzymatic activity of GFPT2, or enhancing flux downstream in the pathway with GlcNAc or potent derivatives, may provide a new class of lysosomal enhancers to combat protein aggregation." (PMID 38897986, 2024).
Uterine leiomyoma (1 paper, 2021). The presence of a leiomyoma of the uterus. "Uterine leiomyomas may indeed have substantially lower metabolic activity also as measured by the GFPT2 protein expression." (PMID 33941787, 2021). "TMAs that we analyzed in the present study included cores from four uterine leiomyomas, all of which were negative for GFPT2 expression (data not shown)." (PMID 33941787, 2021).
uterine tumors (1 paper, 2021). "Among the uterine tumors, 113 were negative and 50 were positive for GFPT2 protein expression." (PMID 33941787, 2021).
Viral infections (1 paper, 2025). "Notably, while UPR signaling often upregulates GFPT2 expression in response to viral infection in human small airway epithelial cells, it specifically promotes GFPT1 expression in cardiomyocytes." (PMID 40830088, 2025). "Viral infections, such as respiratory syncytial virus (RSV), stimulate GFPT2 to drive HBP, leading to increased UDP-GlcNAc synthesis and viral glycoprotein production." (PMID 40830088, 2025).
cancer (31 papers, 2015 to 2025). A tumor composed of atypical neoplastic, often pleomorphic cells that invade other tissues. "GFPT2, specifically, is associated with immunosuppressive cells like M2 macrophages and cancer-associated fibroblasts, contributing to immune evasion." (PMID 40830088, 2025). "GFPT2 expression was linked to cancer-associated fibroblasts (CAFs)-associated factors and epithelial-mesenchymal transition (EMT)-related factors." (PMID 35330716, 2022). "Furthermore, cancer metabolism reprogramming-associated GFPT2+ CAFs were reduced in the PD-1+SMI compared with that in the PD-1 group." (PMID 37430270, 2023). "Our findings revealed a greater incidence of cancer recurrence occurring first in the liver following PaCa resection in patients with elevated GFPT2 expression (n = 30) than in those with low GFPT2 expression (n = 32)." (PMID 38888874, 2024). "This study revealed that GFPT2 expression promoted cancer cell invasion and that this increase in invasion was suppressed by DON, an HBP inhibitor." (PMID 38888874, 2024). "Consistently, GFPT2 is also upregulated in other rapidly proliferating cells with similar metabolic profiles, like in various types of cancer cells." (PMID 35229715, 2022). "Overall, our work largely revealed the roles of GFPT2 in tumorigenesis, especially in immune response, tumor microenvironment and drug resistance, which is crucial for the development of customized cancer therapies." (PMID 35330716, 2022). "Consistent with GFPT2 promoting cancer progression, we find that elevated GFPT2 expression correlates with poor clinical outcome in NSCLC." (PMID 30885209, 2019). "This study supports our findings and suggests that GFPT2 upregulation is a common EMT gene signature in multiple carcinomas, including LUAD." (PMID 30885209, 2019). "Furthermore, GFPT2 expression positively correlated with markers of cancer-associated fibroblasts (CAF), which play a role in cancer cell migration and invasion." (PMID 40830088, 2025). "GFPT2 is quite frequently overexpressed in several carcinomas, which might suggest its importance in cancer metastasis." (PMID 40291779, 2025). "Moreover, GFPT2 expression is enriched in EMT- and ECM-associated cellular populations, including mesenchymal cells, stromal cells, and cancer-associated fibroblasts (CAFs), further underscoring its role in invasion and metastatic dissemination." (PMID 40830088, 2025). "KRAS/LKB1 co-mutant tumors have a higher activation of the hexosamine biosynthesis pathway (HBP), making them more dependent on the HBP enzyme glutamine-fructose-6-phosphate transaminase 2 (GFPT2) and defining a new metabolic vulnerability in such types of cancers." (PMID 35178349, 2022). "Recently, we found another selective vulnerability of these KL co-mutant cancers to inhibition of glutamine-fructose-6-phosphate transaminase 2 (GFPT2), a rate-limiting enzyme in the amino sugar/nucleotide sugar pathway called the hexosamine biosynthesis pathway (HBP)." (PMID 35011738, 2022). "While several factors currently limit its feasibility as a direct therapeutic target, the isoform-specific functions of GFPT1 and GFPT2 present an opportunity to develop cancer subtype-specific biomarkers and may inform the design of more selective therapeutic strategies." (PMID 40830088, 2025). "This suggests that GFPT2+ fibroblasts may be involved in cancer metabolism reprogramming." (PMID 37430270, 2023). "In cancer, the expression of GFPT1 and GFPT2 is differentially regulated under varying cellular stress conditions." (PMID 40830088, 2025). "In non-small cell lung cancer, KRAS/LKB1 co-mutant cancer cells showed high levels of hexosamine biosynthesis pathway (HBP) metabolites, higher flux through the HBP and elevated dependence on the HBP enzyme GFPT2." (PMID 38575607, 2024). "In resistant cancer cells, elevated expression of G6PD, AKR1B1 and GFPT2 counteracts the effects of ROS production as a prerequisite for cell survival and therapy resistance." (PMID 36463238, 2022).
cancer (continued). "Our work reveals the roles of GFPT2 in tumorigenesis, particularly in immune response, TME and drug resistance, which are crucial for the development of customized cancer therapies." (PMID 35330716, 2022). "The differential expression observed in cancer further suggests distinct biological functions for GFPT2 that are not redundant with those of GFPT1." (PMID 40830088, 2025). "In support of this, expression analyses show that high GFPT2 levels are positively correlated with advanced tumor stages in multiple cancer types, a trend not observed for GFPT1." (PMID 40830088, 2025). "In addition, GFPT2 and SRPX2, which are closely related to CPA4, also promote the progression of various cancers." (PMID 38494845, 2024). "Along with GFPT2, various functions of the HBP as well as the O-GlcNAc, which is a post-translational modification using UDP-GlcNAc, the end product of HBP, as a substrate, have also been proposed as targets for cancer treatment." (PMID 38093368, 2023). "A negative correlation between GSH and GFPT2 expression was observed across the NCI60 cancer cell line panel." (PMID 34923141, 2022). "A gene–metabolite correlation analysis of the NCI60 cancer cell line panel indicated a negative correlation between GFPT2 and GSH." (PMID 34923141, 2022). "Hypoxic cancer cells have been shown to contain elevated levels of the HBP genes, including Gln–fructose-6-phosphate transaminase 1 (GFPT1) (which was overexpressed in our study) and GFPT2, and overall O-GlcNAcylation." (PMID 29615075, 2018). "For example, mRNA expression of GFPT2 was higher in samples expressing transcript asm¦1118373 only in normal samples (Fig4C), whereas MGC50722 was higher in samples expressing transcript asm¦33042705 in both cancer and normal samples (Fig4D)." (PMID 26253570, 2015). "Understanding the complex interactions between GFPT2, NKX3-2, Caspases, and Bcl-2 family proteins may offer valuable insights into developing strategies to combat paclitaxel resistance in EOC, guiding the creation of novel therapeutic approaches for this challenging cancer." (PMID 40291779, 2025).
tumor (31 papers, 2014 to 2025). "In EGFR-mutated NSCLC, targeted GFPT2 inhibition restores anti-tumor immunity by enhancing CD8 + T cell infiltration and reducing immune checkpoint activity." (PMID 40830088, 2025). "We found that GFPT2 was generally more highly expressed in tumor tissues and that the high expression of GFPT2 was associated with worse prognosis." (PMID 38575607, 2024). "We found GFPT2 was generally more highly expressed in PDAC tumor tissues and that the high expression of GFPT2 was associated with worse prognosis." (PMID 38575607, 2024). "This bias suggests that elevated GFPT2 expression was caused not only by neoadjuvant chemotherapy but also by tumor progression." (PMID 38888874, 2024). "Notably, accumulating evidence indicates that GFPT1 is more closely associated with tumor growth and proliferation, whereas GFPT2 correlates with tumor metastasis and progression." (PMID 40830088, 2025). "We found that OSMI-1 significantly inhibited tumor proliferation caused by GFPT2." (PMID 38575607, 2024). "Interestingly, the high levels of GFPT2 were significantly and negatively linked to tumor purity (R=0.82, P<0.0001), suggesting that GFPT2 mainly affects the predominant activity of TME, which has essential position in stromal cell and immune cell infiltrations." (PMID 35330716, 2022). "Thus, we hypothesized that such selective growth defects of KL co-mutant cells caused by GFPT2 inhibition are associated with a selective reduction of the tumor-associated glycans in KL cells." (PMID 35011738, 2022). "Tumor cells overexpressing glutamine‐fructose‐6‐phosphate transaminase 2 (GFPT2) deplete extracellular glutamine, impairing mitochondrial fission and the phagocytic capacity of TAMs." (PMID 40904700, 2025). "Supplementing glutamine or targeting GFPT2 can restore macrophage phagocytic activity towards tumor cells." (PMID 39905317, 2025). "Here, we demonstrated that GFPT2 regulated O-GlcNAcylation modifications in tumor cells and then promoted macrophage M2 polarization and the malignant phenotype of PDAC." (PMID 38575607, 2024). "More importantly, targeting GFPT2 reduced KRAS/LKB1 co-mutant tumor cell growth in in vitro and in vivo models." (PMID 38575607, 2024). "To confirm this assumption, we measured the overall levels of O-GlcNAcylation in tumor tissues and found that tumor tissues with high expression of GFPT2 tended to have high overall levels of O-GlcNAcylation." (PMID 38575607, 2024). "In live tumor cells, GFPT2 overexpression promoted the excessive use of glutamine by tumor cells and competitively impaired the uptake of glutamine by macrophages." (PMID 38575607, 2024). "GFPT2 is predominantly expressed in invasive-edge CAFs and is a key regulator of tumor metabolic reprogramming." (PMID 37143134, 2023). "Expression of GFPT2 in single cell subpopulations was calculated from The Tumor Immune Single Cell Center (TISCH)." (PMID 35330716, 2022). "Both GFPT2 silencing and pharmacological GFPT inhibition (azaserine) selectively reduced tumor-associated glycan structures in KL co-mutant cells." (PMID 35011738, 2022). "In agreement with our findings, a previous microarray comparing C4-HD and C4-HI tumours found upregulation of glutamine-fructose-6-phosphate aminotransferase 2 (GFPT2, which controls the flux of glucose into the hexosamine pathway)." (PMID 35299741, 2022). "The most frequent location of metastasis was in the lungs and 82% (23/28) of lung metastases showed the same pattern of GFPT2 expression as the primary tumor." (PMID 33941787, 2021). "A para-rectal LMS tumor with strong expression of GFPT2 protein had a very high glucose consumption expressed as the maximum standardized uptake value (SUVmax = 63)." (PMID 33941787, 2021). "In our studies, we found that GFPT2 is transcriptionally upregulated in response to TNF, or combinations of TNF and TGFβ treatments, suggesting that GFPT2 expression is upregulated in response to inflammatory cytokines present in the tumor microenvironment." (PMID 30885209, 2019).